IDO1 (indoleamine 2,3-dioxygenase 1)
Diseases named in the same sentence as IDO1 in open-access papers (continued):
Sharing a sentence is not in itself a finding about the gene and the disease.
cyst (2 papers, 2023 to 2025). A sac-like closed membranous structure that may be empty or contain fluid or amorphous material. "Genetic loss and pharmacological inhibition of IDO1 slowed cyst growth in our model." (PMID 36422996, 2023). "Ido1 loss is associated with a CME favorable to halting cyst progression." (PMID 36422996, 2023). "SEM analysis also revealed that the NETs that formed in IDO1-KO mice after cyst fluid stimulation were more “loose” than those in WT mice." (PMID 40597301, 2025). "Given our previously published findings that CD8+ T cells play an anticystogenic role in the Pkd1RC/RC model, this increase in CD8+ T cell numbers supports a reduction in cyst severity in PKD Ido1–/– animals compared with control." (PMID 36422996, 2023). "Pharmaceutical inhibition of IDO1 slows cyst growth in a slowly and rapidly progressive model of PKD as well as changes the CME toward an anticystogenic composition." (PMID 36422996, 2023). "Indeed, it appears that cyst growth from 3 to 6 months of age in Pkd1RC/RC;Ido1–/– mice was halted compared with controls, as evidenced by a significant reduction in kidney cyst count and size." (PMID 36422996, 2023). "However, Pkd1RC/RC mice showed increased levels of IDO1 expression in cyst-lining cells and interstitial cells." (PMID 36422996, 2023). "Since genetic loss of Ido1 or 1-MT treatment in our PKD model not only reduced kidney kynurenine/kynurenic acid levels, but also slowed cyst growth, we hypothesized inhibition of immunosuppressive pathways to be an underlying mechanism." (PMID 36422996, 2023). "To further validate our findings, we isolated neutrophils from WT uninfected mice and cocultured them with an IDO1 inhibitor, an IL8 inhibitor, or cyst fluid." (PMID 40597301, 2025). "To further validate our conclusions, we isolated neutrophils from WT and IDO1-KO uninfected mice and cocultured them with PMA or cyst fluid." (PMID 40597301, 2025).
Dengue (2 papers, 2020 to 2022). "Low circulating levels of tryptophan, and increased IDO-1 activity in patients with dengue were previously demonstrated." (PMID 35456119, 2022). "During DENV infection, low levels of tryptophan and increased IDO-1 activity were observed in patients with mild dengue disease." (PMID 35456119, 2022). "As Dengue patients seem to present with lower tryptophan and higher kynurenine concentrations in the serum, we decided to include IDO1 and IDO2 genes in the analysis." (PMID 32117223, 2020).
eczema herpeticum (2 papers, 2022 to 2025). "Low VEGF levels are linked to persistent AD, while IDO1 offers potential insights into complications such as eczema herpeticum." (PMID 40141720, 2025). "A low serum VEGF level has been found to predict the AD persistence in infancy, while the enzyme indoleamine 2,3-dioxygenase-1 (IDO1) has been proposed as a prognostic candidate biomarker for the development of eczema herpeticum and other viral complications in AD patients." (PMID 40141720, 2025).
endometrial tumors (2 papers, 2015 to 2023). "A different aspect of IDO1 expression centers on cancer biology, where some tumor types (especially ovarian and endometrial tumors) express IDO1." (PMID 37196768, 2023).
fibromyalgia (2 papers, 2024 to 2025). A chronic disorder of unknown etiology characterized by pain, stiffness, and tenderness in the muscles of neck, shoulders, back, hips, arms, and legs. "Therefore, in fibromyalgia, lymphocyte activation leads to increased production of pro-inflammatory cytokines and heightened IDO1 activity." (PMID 39857723, 2025).
hemophilia A (2 papers, 2020 to 2025). The most common form of hemophilia characterized by spontaneous or prolonged hemorrhages due to factor VIII deficiency. "Specifically, in a cohort of 100 severe hemophilia A patients, the inhibitor-positive status was associated with dysfunctional activation of IDO1 in human CD11c+ APCs in response to the “environmental danger signal” CpG ODN acting as ligand for the Toll-like receptor 9 (TLR9)." (PMID 32351505, 2020). "For instance, IDO1 and HMOX1 have specifically been associated with a lower incidence of FVIII inhibitors in people with hemophilia A." (PMID 41573577, 2025). "The reduction of FVIII-specific CD4+ T cell activation, as well as amplification of regulatory subsets of T cells by IDO1 represents a potential mechanism for tolerance induction and a possible strategic means to restrain the anti-FVIII immune response in hemophilia A." (PMID 32351505, 2020). "In F8 KO mice, the animal model of hemophilia A, CpG-ODN administration and consequent induction of IDO1 in dendritic cells (DCs) was shown to prevent generation of anti-FVIII antibodies while promoting FVIII-specific FoxP3+ Tregs, which effects required both IDO1 and AhR in host immune cells." (PMID 32351505, 2020).
Hypertryptophanemia (2 papers, 2019 to 2022). "And secondly, hypertryptophanemia can compromise the peripheral tryptophan depletion triggered by IDO1 and abolish local immunosuppression." (PMID 36188218, 2022).
idiopathic pneumonia syndrome (2 papers, 2023 to 2024). "This cell-intrinsic IDO1-AHR pathway represses STAT1-mediated IL6 expression and subsequently prevents CD4+ T cells from differentiating into pathogenic Th17 cells, which are a major effector responsible for idiopathic pneumonia syndrome (IPS)." (PMID 37394584, 2023).
kidney damage (2 papers, 2022 to 2023). "In addition, increased IDO1 abundance and stress gene expression was shown in kidney tissue from patients with Ab-driven nephropathy." (PMID 37509627, 2023).
mastitis (2 papers, 2017 to 2023). Inflammation of breast tissue during lactation or postpartum due to an obstructed duct or infection. "Another significant feature of the mammary host response was the significant enrichment of the DEGs involved in chronic inflammatory response (CXCL13, IDO1 and S100A8) that led to the mastitis phenotype." (PMID 28081235, 2017).
mastocytoma (2 papers, 2021 to 2023). A localized tumor composed of sheets of mast cells without atypia. "Before investigating the effect of epacadostat on IDO1-mediated signaling, we tested the ability of this compound to inhibit the enzymatic activity of IDO1 in the mastocytoma cell line P1.HTR stably expressing the mouse IDO1 protein (P1.IDO1)." (PMID 37122718, 2023).
memory impairment (2 papers, 2016 to 2020). "The results indicated that IDO1 was involved in the development of memory impairment in mice exposed to alcohol." (PMID 32116558, 2020).
meningioma (2 papers, 2020 to 2021). A generally slow growing tumor attached to the dura mater. "INFγ that is highly expressed in both GBM-s and meningiomas stimulates tissue macrophages to produce a higher level of IDO1, which via alteration of cytokine levels inhibits the proliferation of effector T cells." (PMID 35366268, 2021).
meningitis (2 papers, 2011 to 2021). A disorder characterized by acute inflammation of the meninges of the brain and/or spinal cord. "Additionally, in a pattern similar to that observed in A129 mice treated with 1-MT, brain histopathological analysis of C57BL/6 and IDO-1-/- infected mice revealed mild gliosis and meningitis in both infected experimental groups." (PMID 34335614, 2021).
metastasis (2 papers, 2020 to 2024). The spread or migration of cancer cells from one part of the body (where they first appeared) to another. "Elevated levels of indoleamine 2,3-dioxygenase-1 have been associated with increased bone metastasis in BC patients." (PMID 38187259, 2024).
Opportunistic infection (2 papers, 2022 to 2025). An infection that is caused by a pathogen that would generally not be able to cause an infection in a host with a normal immune system. "Furthermore, these data suggest that IDO1 or AHR are potential host targets for the prevention of opportunistic infections in patients undergoing antimicrobial therapy." (PMID 40387573, 2025).
papilloma (2 papers, 2022 to 2023). A benign epithelial neoplasm that projects above the surrounding epithelial surface and consists of villous or arborescent outgrowths of fibrovascular stroma. "While papilloma development was significantly impaired by IDO1 gene deletion, this effect was unrelated to any discernable reduction in the degree of inflammation elicited by TPA treatment." (PMID 37182174, 2023). "Notably, TPA treatment was found to stimulate IDO1 induction within dendritic cells in the regional lymph nodes, and genetic ablation of IDO1 substantially reduced the number of papillomas that formed in DMBA/TPA treated mice relative to their WT (wild type) counterparts." (PMID 37182174, 2023). "In a mouse papilloma model, it was later shown that genetic deletion of IDO1, but not GCN2, inhibited skin carcinogenesis, implying that additional critical pathways existed downstream of IDO1 activation." (PMID 35918736, 2022). "Furthermore, when TPA was eliminated from the carcinogenesis process by instead eliciting tumors though multiple rounds of DMBA application, IDO1 gene deletion had no demonstrable impact on the incidence of papilloma formation." (PMID 37182174, 2023).
periodontal disease (2 papers, 2020 to 2024). "Since cytokine levels vary during periodontal disease progression, the observed temporal reduction of IDO-1 productions and its enzymatic activity may have a physiological significance." (PMID 33339125, 2020).
pulmonary arterial hypertension (2 papers, 2018 to 2024). Pulmonary arterial hypertension (PAH) is a group of diseases characterized by mean pulmonary artery pressure >20 mmHg and elevated pulmonary arterial resistance leading to right heart failure. "Moreover, experiments conducted in mice confirmed an increase in IDO1 levels in the context of pulmonary arterial hypertension, suggesting that specific enzymes and metabolites within the kynurenine pathway may serve as promising biomarkers for discerning abnormal pulmonary vascular function." (PMID 38883986, 2024). "In addition to regulating inflammation, induction of IDO1 expression in pulmonary endothelial cells has been shown to reverse pathological vascular proliferation and modulate VSMC phenotype transformation, thereby attenuating vascular remodeling in pulmonary arterial hypertension." (PMID 38883986, 2024).
relapsing-remitting MS (2 papers, 2020). "Not so long ago, decreased IDO-1 expression and KYN levels (but not TDO expression) were found in the peripheral blood monocytes (PBMC) of relapsing-remitting MS (RRMS) patients compared to healthy controls." (PMID 32604956, 2020).
scrub typhus (2 papers, 2012 to 2020). Scrub typhus is a rare dust mite-borne infectious disease caused by the Orientia tsutsugamushi bacterium and characterized clinically by an eruptive fever which is potentially serious. "This is of interest because indoleamine 2,3-dioxygenase (Ido1), another gene product involved in catabolizing of tryptophan, is up-regulated in scrub typhus patients." (PMID 31906849, 2020). "In conclusion, this is the first report for IDO1 activation in patients with scrub typhus, which has brought this multifaceted gene with promising therapeutic potential into focus in the field of scrub typhus research." (PMID 22860140, 2012). "Our earlier genome-wide expression study revealed up-regulation of a tryptophan-catabolizing enzyme, indoleamine 2,3-dioxygenase (IDO1), in patients with scrub typhus." (PMID 22860140, 2012). "We hypothesized that up-regulation of IDO1 upon infection with scrub typhus could lead to rescriction of OT growth in host cells according to the fact that OT lacks an enzyme to generate tryptophan, which is an essential material for its expansion." (PMID 22860140, 2012). "Thus, activation of IDO1 was first confirmed at functional level in patients with acute scrub typhus in the present study." (PMID 22860140, 2012). "However, further studies are deserved to investigate other potential effects of IDO1 activation on the outcome of OT infection in a more complex experimental model as well as in more patients with scrub typhus." (PMID 22860140, 2012). "In the present study, we reported that IDO1 acitivity was increased in patients with scrub typhus." (PMID 22860140, 2012). "Seeing that similar serious conditions are also common in severe cases of scrub typhus, activation of IDO1 might be involved in the development of such complications; its high functional activity could be a poor prognostic marker for this life-threatening disease as well." (PMID 22860140, 2012). "Our work not only provided the first link of in vivo activation of IDO1 and IFN-γ-mediated protection against OT infection but also highlighted the promise of this multifaceted gene in scrub typhus research." (PMID 22860140, 2012). "Our work provided not only the first link of in vivo activation of IDO1 and IFN-γ-mediated protection against OT infection but also highlighted the promise of this multifaceted gene in scrub typhus research." (PMID 22860140, 2012). "However, the role of IDO1 in scrub typhus has never been directly investigated." (PMID 22860140, 2012).
soft tissue sarcoma (2 papers, 2018 to 2021). A malignant neoplasm arising from muscle tissue, adipose tissue, blood vessels, fibrous tissue, or other supportive tissues excluding the bones. "Indoleamine 2,3 dioxygenase (IDO1), the rate-limiting enzyme of the kynurenine pathway, and programmed cell death 1 ligand 1 (PD-L1) are potential immunotherapeutic targets against soft tissue sarcoma." (PMID 34513839, 2021).
Splenomegaly (2 papers, 2013 to 2016). Abnormal increased size of the spleen. "Profound reduction in MuLV-induced pain hypersensitivity did not correlate with major changes in virus titers or host immunopathogenesis (splenomegaly, immunosuppression, cytokine induction) since these parameters were comparable in WT and IDO1-KO mice." (PMID 27168185, 2016).
thyroid tumor (2 papers, 2020 to 2021). A benign or malignant neoplasm affecting the thyroid gland. "Several studies already described an abundant presence of immune cells in BRAF V600E positive thyroid tumors with more aggressive behavior, as well as higher expression of immune evasion genes such as PD-L1, IDO1, and CTLA-4." (PMID 34680332, 2021). "Moreover, the researchers, through in vitro co-culture experiments, provided evidences that IDO1-expressing thyroid tumor cells strongly inhibited proliferation of activated T lymphocytes and specifically increased the differentiation of Treg cells." (PMID 33986723, 2020).
viral hepatitis (2 papers, 2021). An acute or chronic inflammation of the liver parenchyma caused by viruses. "More surprisingly, in viral hepatitis, the inhibition of TDO or IDO (both IDO1 and IDO2) separately leads to dichotomous outcomes." (PMID 35003126, 2021).
Zika virus infection (2 papers, 2020 to 2021). "In view of the effects observed after 1-MT treatment and the potential contribution of this pathway in preventing neurodegeneration, we also evaluated ZIKV infection in genetically modified Indoleamine 2,3-dioxigenase 1 deficient (IDO-1-/-) mice." (PMID 34335614, 2021). "In this context, we next, evaluated the effects of the inhibition of IDO-1 on ZIKV infection in vitro and in vivo systems." (PMID 34335614, 2021). "In the current study, we showed that ZIKV infection increased levels of IDO-1 expression in mice’s brain and also in primary neuron culture obtained from embryonic brains of mice." (PMID 34335614, 2021). "Overall, these data indicate a neuroprotective effect induced by IDO-1 inhibition after ZIKV infection in vivo and in vitro." (PMID 34335614, 2021). "After 48 hours of ZIKV infection, there was an increase in the levels of IDO-1 when compared to Mock control in primary neuron cultures." (PMID 34335614, 2021). "Similar to JEV, Zika virus infection induces indoleamine 2,3-dioxygenase 1 (IDO-1) expression in dendritic cells of human patients, which is thought to antagonize host antiviral immunity through Treg induction." (PMID 32131483, 2020). "We also evaluated ZIKV infection in IDO-1-/- mice and WT mouse model." (PMID 34335614, 2021). "Further, we investigated the effects of IDO-1 inhibition during ZIKV infection in vivo." (PMID 34335614, 2021). "Since C57BL/6 mice are resistant to ZIKV infection, ZIKV infection was performed by intracerebral route by inoculation of with 1 x 106 PFU of ZIKV (i.c) in both WT C57BL/6 and IDO-1-/- mice." (PMID 34335614, 2021). "The main results were: (I) increased levels of IDO-1 expression after ZIKV infection; (II) reduction of neuronal death upon 1-MT treatment; (III); massive reduction of ZIKV-induced microgliosis, astrogliosis and apoptosis in IDO-/- mice and after 1-MT administration in A129 mice." (PMID 34335614, 2021). "Finally, as demonstrated during 1-MT treatment, intracranial ZIKV infection also led to increased production of inflammatory mediators, such as CCL5 and CXCL1 in both WT and IDO-1-/- ZIKV mice." (PMID 34335614, 2021). "Further studies are required to elucidate the mechanisms of neuroprotection obtained by ablation of IDO-1 and it will be important to evaluate whether the combination of neuroprotective drugs, such 1-MT, and antiviral like AH-D or DFMA could be the treatment for ZIKV infection." (PMID 34335614, 2021).
abscess (1 paper, 2025). An inflammatory process characterized by the accumulation of pus within a newly formed tissue cavity which is the result of a bacterial, fungal, or parasitic infection or the presence of a foreign body. "We hypothesize that the IL2RA+ M1-like clusters make up the macrophage collar that surrounds the abscess, since they express transcripts corresponding to IDO1, anti-oxidative defenses, and MMPs." (PMID 39882906, 2025).
allergic bronchopulmonary aspergillosis (1 paper, 2012). Allergic bronchopulmonary aspergillosis (ABPA) is a rare immunologic pulmonary disorder caused by hypersensitivity to Aspergillus fumigatus, clinically manifesting with poorly controlled asthma and recurrent pulmonary infiltrates. "Glucocorticoids can activate IDO1 via glucocorticoid-induced tumor necrosis factor receptor (GITR) and protect against allergic bronchopulmonary aspergillosis." (PMID 22844400, 2012).
anal squamous cell carcinoma (1 paper, 2023). A squamous cell carcinoma (SCC) arising from the anal canal or the anal margin (perianal skin). "As an example, anal squamous-cell carcinoma was associated with high IDO1 expression to a very high degree, correlating with a worse survival rate (88%) compared with low-IDO1-expression tumors (25%)." (PMID 37296860, 2023).
atopic asthma (1 paper, 2021). An asthma that is characterized by symptoms that are triggered by an allergic reaction caused by inhaled allergens such as dust mite allergen, pet dander, pollen and mold. "High exhaled nitric oxide (eNO) levels are features of atopic asthma, and suppression of tryptophan-degrading enzyme indoleamine 2, 3-dioxygenase-1 (IDO-1) by NO could explain high tryptophan levels in childhood asthma." (PMID 33919626, 2021).
autoimmune encephalitis (1 paper, 2021). Inflammation of the brain secondary to an immune response triggered by the body itself. "Also, compared with controls, both patients with primary epilepsy and patients with seizures secondary to autoimmune encephalitis displayed a progressive increase in IDO1 activity in the serum." (PMID 33679331, 2021).
bacterial vaginosis (1 paper, 2018). Infection caused by bacterial overgrowth in the vagina. "However, as an immune-suppressor, IDO1 has been found to have beneficial effects in tolerance and one study reported that high kynurenine was associated with a healthy state of the vaginal microbiome in comparison to women with bacterial vaginosis (BV)." (PMID 29404279, 2018).
brain edema (1 paper, 2020). Increased intracellular or extracellular fluid in brain tissue. "The IDO1 + group had a higher incidence rate of brain edema than the IDO1− group, although this difference was not statistically significant." (PMID 32296044, 2020).